ORAI3 (ORAI calcium release-activated calcium modulator 3)
Diseases named in the same sentence as ORAI3 in open-access papers (continued):
Sharing a sentence is not in itself a finding about the gene and the disease.
breast carcinoma (continued). "In breast cancer cells, we have previously shown that Orai3 silencing induced cell cycle arrest in the G1 phase." (PMID 24058448, 2013). "This may be explained by its known activation of Orai3 channels in estrogen receptor-positive breast cancer cells, as previously reported." (PMID 40869089, 2025). "Orai3 has been presented as an oncogene and plays an important role in supporting a number of hallmarks in different tumoral cell types, such as pancreatic adenocarcinoma, prostate and luminal breast cancer cells." (PMID 38514909, 2024). "In addition, recent data suggest that ORAI3 plays crucial role in calcium regulation of ER + breast cancer cells in particular, and is capable of complexing with ORAI1 to form heteromultimeric channel." (PMID 37400769, 2023). "Thus, it is important to focus on cancer type-specific deregulated pathways in therapy development, such as the unique SPCA2-Orai1 or SK3-Orai1 co-regulation in breast cancer or the specific role of Orai3 in various cancer types." (PMID 36612099, 2022). "For example, studies have shown that Orai3 is involved in various processes of breast cancer, such as proliferation and survival and resistance to chemotherapy, and the expressions of secretory pathway Ca2+-ATPases (SPCA1) and SPCA2 genes are significantly increased in breast cancer." (PMID 36230965, 2022). "In ER+ breast cancer cells, Orai3 expression plays a relevant role in the maintenance of a variety of cancer hallmarks, including cell cycle progression, cell proliferation, migration, and cell survival, thus unveiling the potential role of Orai3 as a therapeutic target for antitumoral strategies." (PMID 34768857, 2021). "In addition, to its role in cell proliferation and migration in ER+ breast cancer cells, Orai3 has been reported to be involved in breast cancer cell resistance to chemotherapeutic drugs." (PMID 34768857, 2021). "Similarly, Orai3 was recently demonstrated to regulate EMT in breast cancer cells by modulating the expression of key EMT transcription factor Snail." (PMID 34885048, 2021). "In addition to promoting the migration and invasiveness of renal cancer cells, the upregulated expression of TRPC6 is also required for translocation of Orai1 and Orai3 to the plasma membrane of metastatic breast cancer cells." (PMID 36046433, 2021). "Our results suggest a specific effect of Orai3 depending on the ER status of breast cancer cells." (PMID 34943998, 2021). "Functional studies in ER+ breast cancer cells combined with bioinformatic analysis have demonstrated that miR18a and miR18b positively regulate Orai3 expression and function while miR34a represses Orai3 expression by inducing translational block." (PMID 34768857, 2021). "Orai3 has mainly been studied in ER+ breast cancer cell lines where it participates in the SOCE." (PMID 34943998, 2021). "We were first to show that Orai3 regulates breast cancer tumorigenesis in vivo." (PMID 34885048, 2021). "Orai3 has also been reported to be expressed in triple-negative MDA-MB-231 breast cancer cells." (PMID 34768857, 2021). "ORAI3 has gained increased interest because it is overexpressed in cancer, in particular estrogen receptor-expressing breast cancer cells, where it contributes to cancerous properties by inducing calcium influx, phosphorylation of ERK, and expression of c-myc21,23–29." (PMID 33568645, 2021). "Moreover, transient receptor potential canonical 6 (TRPC6) channel has been reported to regulate plasma membrane translocation of Orai3 as well as Orai1 in breast cancer cell line." (PMID 34360783, 2021). "In conclusion, we show that Orai3 mediates basal Ca2+ entry in basal-like breast cancer cells." (PMID 34943998, 2021). "However, very few studies have been conducted to understand the role of Orai3 in the basal-like ER− type breast cancer cell lines." (PMID 34943998, 2021).
breast carcinoma (continued). "Moreover, the Orai3 level is upregulated in breast cancer patients and is correlated with poor response to chemotherapy and poor patient outcome." (PMID 32575381, 2020). "Likewise, lower levels of ORAI3 would indeed be predicted in the breast cancer cells with high levels of NCS‐1 since ORAI3 levels are found to be lower in basal breast cancers, which we have shown to have higher levels of NCS‐1." (PMID 31647602, 2020). "Likewise, Orai3 overexpression in T47D breast cancer cells confers resistance to pro-apoptotic agents (thapsigargin and staurosporine) and chemotherapeutics (cisplatin, 5-FU, and paclitaxel)." (PMID 32575381, 2020). "Another independent study led by Faouzi also demonstrated that Orai3 knockdown impaired breast cancer MCF-7 cell proliferation and arrested cell cycle progression at the G1 phase without affecting the proliferation and survival of wild-type mammary MCF-10A cells." (PMID 32599788, 2020). "Given the reports of ORAI3 contribution to SOCE in ERα-positive breast cancer cell lines with high levels of ORAI3, we assessed whether ORAI3 contributed to SOCE in MDA-MB-468 cells after its induction by hypoxia." (PMID 30754719, 2019). "ORAI1 is a well-characterized regulator of the proliferation and migration of many basal breast cancer cells; however, the role of ORAI3 in these types of breast cancer cells remains unclear." (PMID 30754719, 2019). "Our RNA-Seq experiments assessing the consequences of ORAI3 silencing on alterations in gene expression induced by hypoxia in MDA-MB-468 basal breast cancer cells further identified specific functions that may be regulated by ORAI3 in basal breast cancers." (PMID 30754719, 2019). "Additionally, Orai3 expression was increased in tumor tissues of lung adenocarcinoma, prostate cancer, and breast cancer and correlated with overall survival and metastasis-free survival." (PMID 30935064, 2019). "The sensitivity of ORAI3 expression to hypoxia was assessed in breast cancer cells." (PMID 30754719, 2019). "However, ORAI3 does control SOCE in many estrogen receptor-positive breast cancer cell lines, where it also controls proliferation." (PMID 30754719, 2019). "Our analysis also suggests that in addition to the previously defined potential for the ERα to contribute to ORAI3 expression in breast cancer cells, overexpression of ORAI3 in some breast cancers may be a consequence of increased gene copy number." (PMID 30754719, 2019). "Indeed, over 50% of breast cancers of the luminal A subtype had a gain or high gain in ORAI3 gene copy number." (PMID 30754719, 2019). "These ORAI3-sensitive genes may play important roles as breast cancer cells escape the hypoxic primary tumor microenvironment." (PMID 30754719, 2019). "Our observation of poorer RFS in some breast cancer subtypes with high ORAI3 and low ORAI1 levels, is reflective of the association between the ORAI1 activators STIM1/STIM2 in basal breast cancers, where high STIM1/low STIM2 was associated with poorer survival." (PMID 30754719, 2019). "Indeed, our data showed that ORAI3 levels are significantly lower in basal breast cancers compared to all other molecular subtypes." (PMID 30754719, 2019). "The silencing of ORAI3 attenuated hypoxia-associated phosphorylation of the EGF receptor (EGFR) and the expression of genes associated with cell migration and inflammatory/immune responses in the MDA-MB-468 model of basal breast cancer." (PMID 30754719, 2019). "In breast cancer, ORAI3 knockdown might halt cancer mitosis, eventually inhibiting cancer proliferation as well." (PMID 29949888, 2018). "The development of a new generation of pharmacological tools against channels selectively expressed in different breast cancer subtypes, such as Orai3, might provide interesting results." (PMID 30558192, 2018). "Indeed, in breast cancer, Orai3 is regulated by the ERα, thereby conferring apoptosis resistance and cell proliferation." (PMID 27835593, 2016).
breast carcinoma (continued). "Indeed, in breast cancer, Orai3 is overexpressed and its expression is under the control of estrogen receptor alpha (ERα) that regulates Ca2+ entry, cell proliferation and survival of estrogen receptor-positive MCF-7 cell line." (PMID 27835593, 2016). "Moreover, Orai3 plays a role in apoptotic resistance in breast cancer cells." (PMID 36612099, 2022). "Interestingly, store-operated calcium (Ca2+) entry (SOCE) is mediated by Orai3 only in breast cancer cells that express the estrogen receptor, contrary to estrogen receptor-negative cancer cells, which suggests a relationship between estrogen concentration and ORAI3 expression." (PMID 32961898, 2020). "Thus Orai3 channels could also represent a target of interest for the treatment of the estrogen-receptor-positive breast cancer cells which represent 80% of breast cancers." (PMID 33371518, 2020). "Besides Orai1, Orai3 seems to play a role in breast cancer development." (PMID 33333945, 2020). "Whilst far less studied than its sibling Orai1, Orai3 protein deserves special attention, because of (i) its exclusive presence in mammals, (ii) its receptivity to pharmacological modulation, and (iii) its recent emergence in the cancer field, especially in breast cancer." (PMID 30884858, 2019). "Moreover, high ORAI3/ORAI1 ratio was shown to correlate with poor prognosis in breast cancer." (PMID 31010205, 2019). "Hence, there may be multiple drivers for the up-regulation of ORAI3 in ERα-positive breast cancers, which include the ERα itself and increased copies of the ORAI3 gene region." (PMID 30754719, 2019). "However, since the Orai3 expression in breast cancer is highly dependent on the ERα expression itself, one might speculate that the Orai1 complexes contribute significantly to Ca2+ signals in ERα negative cells." (PMID 30935064, 2019). "The scenario becomes even more complicated when considering that Orai3 is activated by Stim1 upon intracellular store depletion in some oestrogen receptor-positive breast cancer lines, and that Orai1 may assemble into a supramolecular ternary complex with Stim1 and TRPC1." (PMID 25126575, 2014). "It has also been shown that Orai3 is selectively overexpressed in luminal A breast cancer cells where both SOCE and the development of different cancer features such as cell migration and proliferation are greatly dependent on Orai3." (PMID 37259313, 2023). "In ER+ breast cancer cells, SOCE is mediated exclusively by Orai3 and STIM1/STIM2, whereas in ER- breast cancer cells, the canonical CRAC channel consists of STIM1/Orai1, which is sufficient to trigger SOCE." (PMID 36612099, 2022). "Orai3 and STIM2 also promote gastroenteropancreatic neuroendocrine and breast cancer metastasis, respectively." (PMID 36046433, 2021). "As the effects of these novel compounds were investigated on native SOC of breast cancer cells (MDA-MB-231) and HEK 293 cells, their effects on Orai1 and Orai3 individually remain of interest to determine potential isoform-specificity." (PMID 34360783, 2021). "Orai3 is selectively overexpressed in luminal A breast cancer cells, where SOCE, as well as the development of different cancer features including cell migration and proliferation, strongly depends on Orai3." (PMID 35008277, 2021). "In ER+ breast cancer cell lines, SOCE has been reported to be strongly dependent on Orai3 expression, while Orai1 knockdown in these cells was predominantly without effect, in contrast to the observations in triple-negative breast cancer cell lines." (PMID 34768857, 2021). "Especially for estrogen receptor-expressing (ER+) breast cancer and non-small cell lung cancer (NSCLC), there is ample evidence that Orai3 functions as an attractive therapeutic target in these pathogenic cell types." (PMID 34360783, 2021).
breast carcinoma (continued). "ORAI3, a SOCE component, is overexpressed in breast cancer biopsy samples and is involved in breast cancer cell proliferation and cell cycle progression by modulating the G1 phase and G1/S transition regulator protein activity." (PMID 33171939, 2020). "For instance, we previously showed that upregulated ORAI3 contributes to native SOCE and tumorigenesis in a specific subset of breast cancer cells." (PMID 32415068, 2020). "About Orai3; there exists a dichotomy between SOCE observed in breast cancer cell lines and in cells from patient samples." (PMID 33371518, 2020). "Expression of Orai1 was elevated in MDA-MB-231 cells, while the luminal breast cancer cell type MCF7 exhibited high expression of Orai1 and Orai3 and low expression of STIM1 compared with MCF10A." (PMID 32392840, 2020). "In the breast cancer cell lines MCF7 and MDA-MB-231 cells, the silencing of Orai3 and Orai1 expressions reduced cell proliferation and tumorigenic properties." (PMID 31973006, 2020). "The potential role of increased gene copy number on ORAI3 and ORAI1 expression in breast cancer subtypes was also evaluated." (PMID 30754719, 2019). "Orai3 silencing reduced the in vitro anchorage-independent growth and in vivo tumor xenograft growth of ER-positive MCF-7 breast cancer cells." (PMID 31252656, 2019). "Breast cancer cells from the different subtypes undergo remodeling of the expression of specific molecular SOCE components, including Orai1, Orai3, TRPC1 and even TRPC6." (PMID 30558192, 2018). "In this study, ORAI3 down-regulation specifically reduced the expression and activity of c-Myc via the mitogen-activated protein kinase (MAPK) pathway, leading to breast cancer cell arrest in the G1 phase." (PMID 27013185, 2016). "In contrast, in ER+ breast cancer cells lacking Orai3 overexpression, Sek-1 phosphorylates NEDD4L, subsequently inducing its inactivation via sequestration of the 14-3-3 protein." (PMID 38027016, 2023). "Moreover, in breast cancer cells, TRPC6 was shown to be required for the Tg-induced translocation of ORAI1 and ORAI3 channels to the membrane." (PMID 37108424, 2023). "Specifically, in the estrogen receptor-α (ERα) expressing (ER+) breast cancer cells (MCF-7), Ca2+ entry via Orai3 targets the proto-oncogenic transcription factor c-myc via the MAPK (originally named ERK) pathway to trigger cell proliferation arrest, contributing to ER+ breast tumorigenesis." (PMID 36612099, 2022). "The Orai3-induced Ca2+ influx contributed to breast cancer proliferation and survival but not in normal cells, consistent with the down-regulation of Orai3 arresting cell cycle progression and inducing apoptosis in breast cancer cells." (PMID 36071984, 2022). "In ER+ luminal breast cancer cells this channel regulates proliferation and survival, whereas in ER− basal-like breast cancer cells Orai3 rather regulates migration without affecting cell proliferation and/or survival." (PMID 34943998, 2021). "Interestingly, in breast cancer cells of the luminal subtype (estrogen receptor positive (ER+) breast cancer cells), SOCE is strongly dependent on Orai3 channels, whose expression depends on estrogen receptor-α in these cells, with Orai1 playing a minor role." (PMID 34070268, 2021). "In this work, we confirm that Orai3 is not involved in SOCE in ER− breast cancer cell lines MDA-231 and MDA-BrM2." (PMID 34943998, 2021). "Recently, Monteith’s team made it clear that Orai3 does not constitute a SOC in the ER− breast cancer cell line MDA-MB-468." (PMID 34943998, 2021). "The critical role of Orai3 in cell survival of breast cancer cells came also clear upon siRNA delivery via nanoparticles, which decreased the viability of breast cancer cells (T47D), but not of healthy cell types (MCF10A)." (PMID 34360783, 2021).
breast carcinoma (continued). "Among the exceptions are ER+ breast cancer cells and NSCLC cells, where SOCE is strongly dependent on the Orai3 expression, while knockdown of Orai1 or Orai2 has a minor effect if any, meaning that Orai3 plays a predominant role in SOCE in these cells." (PMID 34768857, 2021). "Orai3 expression is upregulated in ER+ MCF-7 and T47D breast cancer cell lines." (PMID 33333945, 2020). "Similar results are found in breast cancer cells where the downregulation of Orai3 arrests cell-cycle progression and induces apoptosis but not in normal breast epithelial cells." (PMID 30935064, 2019). "In contrast to its major role in the proliferative and invasive properties of ERα-positive breast cancer cell lines, the contribution of ORAI3 to ERα-negative breast cancer cell lines is more specific." (PMID 30754719, 2019). "Motiani and coworkers confirmed that SOCE in triple negative MDA-MB-231 breast cancer cells is entirely dependent on STIM1 and Orai1, while in MCF7, SOCE is mediated by STIM1, STIM2 and Orai3 (overexpressed in this cell line), thus reporting important phenotypic differences between both cell lines." (PMID 30558192, 2018). "Expression of the TRPC6dn significantly attenuated the interaction of TRPC6 with the Orai channels in MCF7 and MDA-MB-231 cells (p < 0.05; n = 4), thus suggesting that TRPC6 channel function is essential for its interaction with Orai3 in MCF7 and Orai1 in MDA-MB-231 breast cancer cells." (PMID 30223530, 2018). "Furthermore, we have reported that Orai3 knockdown inhibits proliferation of MCF-7 and T-47D human breast cancer cells." (PMID 24058448, 2013). "While Orai1 has been clearly shown to encode the SOC pore in many cells, a recent work showed that Orai3 is the SOC pore of estrogen receptor positive breast cancer cell lines, in contrast to estrogen receptor negative cell line which use Orai1." (PMID 21266088, 2011). "In estrogen receptor-positive breast cancer cells and non-small cell lung cancer (NSCLC) cells store-operated Ca2+ entry (SOCE) is strongly dependent on Orai3 expression while in colorectal cancer and pancreatic adenocarcinoma cells Orai3 predominantly modulates SOCE." (PMID 34768857, 2021). "However, the role of Orai3 in estrogen receptor-negative (ER−) breast cancer cells has not yet been tested despite the knowledge of its expression in this cell type." (PMID 34943998, 2021). "Nevertheless, under these conditions, Orai3 knockdown failed to attenuate SOCE, thus suggesting that an alternative mechanism might underlie Orai3 up-regulation and function in ER+ breast cancer cells." (PMID 34768857, 2021). "Furthermore, using the classical SOCE protocol, we confirmed that Orai3 does not participate in SOCE in our breast cancer cell lines." (PMID 34943998, 2021). "Orai3-mediated SOCE in ER+ breast cancer cells has been shown to be modulated by the TRP channel, TRPC6, as TRPC6 knockdown or transient expression of a dominant negative TRPC6 mutant resulted in attenuation of the plasma membrane expression of Orai3 and well as SOCE inhibition in MCF7 cells." (PMID 34768857, 2021). "However, the relationship between ORAI3 levels and breast cancer subtypes has not been extensively evaluated in clinical samples." (PMID 30754719, 2019). "It is specifically interesting to note (given our identification of ORAI3 regulation of both migratory and immune/inflammatory pathways by hypoxia) that PGF is believed to reprogram the tumor immune microenvironment and contribute to obesity-promoted breast cancer progression." (PMID 30754719, 2019). "This lack of correlation may be evidence that ORAI3 is not a driver of cell migration in basal breast cancers, but rather is a fine-tuner of cancer cell migration in some in vivo contexts, through changing the suite of expressed genes in response to specific microenvironmental factors." (PMID 30754719, 2019).